ZCCHC18 (zinc finger CCHC-type containing 18)
Synonyms: SIZN2; PNMA7B
Tractability: No criterion of Open Targets' tractability assessment is met for any kind of drug.
Gene: Protein-coding gene on chromosome X (104,112,060 to 104,115,847, forward strand). Ensembl gene ENSG00000166707.
Subcellular location (Human Protein Atlas): Vesicles
Gene Ontology:
Cellular component: nucleus
Homologues: Orthologues: chimpanzee ZCCHC18 (92% identical), dog ZCCHC12 (82% identical), guinea pig Zcchc12 (80% identical), dog ZCCHC18 (73% identical), mouse Zcchc12 (72% identical), rat Zcchc12 (71% identical), rat Zcchc18 (67% identical), mouse Zcchc18 (67% identical). Paralogues in human: ZCCHC12 (84% identical), PNMA3 (24% identical), PNMA5 (23% identical), PNMA6A (23% identical), PNMA1 (22% identical), PNMA6E (22% identical), PNMA2 (21% identical), PNMA6F (20% identical), MOAP1 (17% identical), CCDC8 (12% identical), PNMA8B (9% identical), PNMA8A (9% identical), and 1 more.
Diseases named in the same sentence as ZCCHC18 in open-access papers:
ZCCHC18 is named in the same sentence as 5 diseases in open-access papers, as found by Europe PMC text mining. Sharing a sentence is not in itself a finding about the gene and the disease. The quoted sentences say what the papers report.
acute lymphoblastic leukemia (1 paper, 2018). Leukemia with an acute onset, characterized by the presence of lymphoblasts in the bone marrow and the peripheral blood. "Some of these genes have already been shown to play a role in hematologic malignancies, including CLL (Pim-2, Met, Rgs16, Ccdc88a, Zcchc18, Clip3), diffuse large B cell lymphoma, follicular lymphoma (Vav3), acute lymphoblastic leukemia (ALL) (Itm2a, Chst1) or acute myeloid leukemia (AML) (Chd3)." (PMID 30271400, 2018).
thyroid cancer (1 paper, 2023). "We also verified the differential expression of ZCCHC gene family genes in commonly used cell lines for thyroid cancer, and all genes were differentially expressed except ZCCHC3 and ZCCHC18." (PMID 37848968, 2023).
ZCCHC18 also shares sentences with these, for which no sentence is quoted: acute myeloid leukemia (1 paper); diffuse large B-cell lymphoma (1); follicular lymphoma (1).